DBH (dopamine beta-hydroxylase)
Description:
Catalyzes the hydroxylation of dopamine to noradrenaline (also known as norepinephrine), and is thus vital for regulation of these neurotransmitters.
Synonyms: DBM; ORTHYP1
Tractability: Small molecule: a drug acting on it is in phase 2 or 3 trials; a high-quality ligand is known; it belongs to a druggable protein family. Antibody: UniProt places it where antibodies can reach, with high confidence; UniProt predicts a signal peptide or a membrane-spanning region; its Gene Ontology location is reachable by antibodies, with medium confidence. PROTAC: a small molecule that binds it is known.
Target class: Enzyme; Oxidoreductase
Safety:
Unwanted effects reported when the protein is acted on. In parentheses: how it was acted on, where the effect was seen, and who reports it.
Decreased, Decreased fecundity (inhibition; source: AOP-Wiki)
memory impairment (source: ClinPGx)
opioid dependence (source: ClinPGx)
Gene: Protein-coding gene on chromosome 9 (133,636,314 to 133,659,329, forward strand). Ensembl gene ENSG00000123454.
Subcellular location: Cytoplasmic vesicle, secretory vesicle lumen (Soluble dopamine beta-hydroxylase); Cytoplasmic vesicle, secretory vesicle, chromaffin granule lumen; Secreted; Cytoplasmic vesicle, secretory vesicle membrane; Cytoplasmic vesicle, secretory vesicle, chromaffin granule membrane
Subcellular location (Human Protein Atlas): Vesicles; Endoplasmic reticulum
Pathways (Reactome):
Metabolism: Catecholamine biosynthesis
Gene Ontology:
Molecular function: copper ion binding; dopamine beta-monooxygenase activity; protein binding; catalytic activity; monooxygenase activity; oxidoreductase activity, acting on paired donors, with incorporation or reduction of molecular oxygen, reduced ascorbate as one donor, and incorporation of one atom of oxygen
Biological process: dopamine catabolic process; norepinephrine biosynthetic process; behavioral response to ethanol; chemical synaptic transmission; positive regulation of cold-induced thermogenesis
Cellular component: extracellular region; secretory granule lumen; secretory granule membrane; cytoplasm; membrane; chromaffin granule lumen; chromaffin granule membrane; cytoplasmic vesicle; synapse; transport vesicle membrane
Genetic constraint (gnomAD): Loss-of-function variants: 49 observed, 66.42 expected, observed/expected ratio (o/e) 0.74, 90% interval 0.59 to 0.94. The upper end of that interval is the gene's LOEUF score, 0.94, which puts it in group 3 of 6, group 1 being the genes least tolerant of losing a copy. Missense variants: 828 observed, 856.55 expected, observed/expected ratio (o/e) 0.97, 90% interval 0.91 to 1.02. Synonymous variants: 343 observed, 361.11 expected, observed/expected ratio (o/e) 0.95, 90% interval 0.87 to 1.04.
Homologues: Orthologues: chimpanzee DBH (99% identical), macaque DBH (91% identical), pig DBH (84% identical), guinea pig DBH (81% identical), mouse Dbh (80% identical), rat Dbh (78% identical), dog DBH (75% identical), tropical clawed frog dbh (64% identical), zebrafish dbh (59% identical), Drosophila melanogaster Tbh (38% identical), Caenorhabditis elegans tbh-1 (34% identical). Paralogues in human: MOXD1 (30% identical).
Diseases named in the same sentence as DBH in open-access papers:
DBH is named in the same sentence as 85 diseases in open-access papers, as found by Europe PMC text mining. Sharing a sentence is not in itself a finding about the gene and the disease. The quoted sentences say what the papers report.
neuroblastoma (12 papers, 1983 to 2022). Neuroblastoma (NB) is the most common solid, extracranial childhood tumor. "Specifically, ETO reduces the expression level of PHOX2B and its known target genes (T-cell leukaemia homeobox 2 and DBH) in neuroblastoma cell lines through activation of the nuclear PGR." (PMID 35563209, 2022). "Genes known to be specifically expressed in neuroblastoma, such as HAND2, PHOX2B, and DBH, were homogeneously expressed across all samples, indicating that the proportion of mRNA derived from neuroblastoma cells was equally distributed between each sample." (PMID 34815394, 2021). "Serum DBH levels in children with neuroblastoma were unrelated to the response of this neoplasm to treatment or to urinary catecholamine output and thus are unlikely to have any value in diagnosis or as a marker of tumour activity." (PMID 6821627, 1983). "Moreover, genes that have previously been established to drive neuroblastoma progression and migration, including DBH, NOTCH1, RET and WNT1, were down regulated in response to TRPM7 knockdown." (PMID 25797249, 2015). "In this study, the gene expression of DBH and PNMT was increased via the down-regulation of the miR-375 level in the IH-treated neuroblastoma cells." (PMID 35682548, 2022). "Biochemical analysis evidenced a decrease of neuronal biomarkers expression and a significant increase of TH, DBH, NSE and CgA, indexes of neuroendocrine differentiation and considered unfavorable prognostic neuroblastoma biomarkers." (PMID 29930753, 2018). "In line with previously published analyses of HOXC9 in neuroblastoma cells, we found a significant up-regulation of genes involved in neuronal differentiation pathways such as DNER, NEFL, DBH, TH, RET, MAP2 and NPY." (PMID 25406647, 2014). "Thus, we exposed catecholamine-synthesizing neuroblastoma cells to IH in the present study and found that IH exposure induced increases in the DBH and PNMT mRNA levels in human neuroblastoma cells." (PMID 35682548, 2022). "Significant expression of (nor-)adrenergic (“NOR”) markers (i.e., CHGA, CHGB, DBH, TH, PHOX2A, and PHOX2B) is common for healthy sympatho-adrenal cells and tumor NOR populations identified in low-risk neuroblastoma cases (FDR < 0.01, Welch’s t-test)." (PMID 34493726, 2021). "Taken together, IH upregulates the mRNA levels of Ren and Cd38 in JG cells via the downregulation of miR-203-mediated mRNA degradation and the mRNA levels of DBH and PNMT in neuroblastoma cells via the inhibition of miR-375-mediated mRNA degradation, which may contribute to hypertension." (PMID 36361741, 2022). "The biochemical differentiation profile of neuroblastoma cells overexpressing TMODs showed a significant increase of MAP2 and GAP43, mimicking then the “neuronal differentiation” obtained by retinoic acid, and an overall decrease of TH, DBH and CgA mRNA expression levels." (PMID 29930753, 2018).
depression (11 papers, 2007 to 2025). "DBH is implicated in many disorders, such as hypertension, congestive heart failure, depression, anxiety, Parkinson’s disease, Tourette syndrome, schizophrenia, and ADHD." (PMID 27152332, 2016). "Both groups demonstrated that plasma DbH activity was significantly lower in alcoholic subjects and in individuals with unipolar major depression with psychotic features, respectively." (PMID 18173840, 2008). "Genes such as DBH, WDR62, NRG1, and FER1L4, identified in hepatic and blood immune transcriptomes, were also implicated in a broad range of disorders, including major depressive disorder, autoimmune diseases, and cancer, which have been previously associated with hepatitis." (PMID 41347690, 2025). "Interference with cAMP-mediated DBH regulation may be involved in the etiology of anxiety and depression symptoms." (PMID 38135278, 2024). "We also found that plasma dopamine beta-hydroxylase (DBH) concentrations increased in responders from 4 to 10 weeks, consistent with low plasma DBH levels associated with low activity of the noradrenaline system in patients with depression." (PMID 33126421, 2020). "Dopamine beta -hydroxylase (DBH) catalyses the key step in biosynthesis of the neurotransmitter noradrenaline from dopamine, and low DBH activity from a variety of brain regions is a possible risk factor for developing depression." (PMID 21494644, 2011). "Some well-known depression candidate genes that do not have scores greater than 0.01 in the HuGE genes are included in our DEPgenes, such as DBH, CHRNA7, and GABRA3, which were all ranked in the top list of DEPgenes." (PMID 21494644, 2011).
schizophrenia (11 papers, 2007 to 2023). A major psychotic disorder characterized by abnormalities in the perception or expression of reality. "The results include a number of diseases associated with neurological and sensory deficits including deafness, blindness, dopamine beta-hydroxylase deficiency, as well as neuropsychiatric disorders including obsessive compulsive disorder and schizophrenia." (PMID 36865388, 2023). "Apart from the 19-bp ins/del polymorphism, other variants such as rs1611115 have been associated with plasma DBH activity in schizophrenia and are a possible biomarker in cerebrospinal fluid for Alzheimer’s disease." (PMID 36143905, 2022). "An rs6271 polymorphism in the DBH gene has also been associated with schizophrenia in a case-control and family-based study from India and bipolar disorder in a study in Turkey." (PMID 36143905, 2022). "Moreover, copper-containing enzymes, including dopamine-beta-hydroxylase and tyrosine hydroxylase, are linked to the synthesis of dopamine and norepinephrine, which have been involved in the etiology of schizophrenia." (PMID 26186003, 2015). "The DBH gene is also related to other neurological diseases such as schizophrenia and Alzheimer’s disease." (PMID 36143905, 2022). "Low DBH activity has been proposed as a biological marker for schizophrenia and other psychiatric disorders." (PMID 28050184, 2016). "In conclusion, the findings of this study showed that a 19-bp ins/del functional polymorphism of DBH gene did not affect the risk of schizophrenia in a sample of Southeast Iranian population." (PMID 28050184, 2016). "Previous studies have indicated that genetic variations of IL 10 and DBH are implicated in the positive and negative symptoms in schizophrenia." (PMID 23951054, 2013). "It has been shown that the del allelic and genotypic frequencies of DBH were significantly lower in controls than in patients with the first-episode of schizophrenia (FES), but controls were not significantly different from chronic schizophrenics (29(." (PMID 28050184, 2016). "The two variations that we genotyped gave us an interaction model of heterozygous, and IL10 and DBH have been identified to influence negative and positive symptoms of schizophrenia, respectively." (PMID 23951054, 2013).
Hypertension (9 papers, 2013 to 2022). The presence of chronic increased pressure in the systemic arterial system. "Controlling for hypertension status gave nearly identical genetic association between DBH p.Arg79Trp and vanillylmandelate (β = −0.38, P = 1.6 × 10−15)." (PMID 35347128, 2022). "Posttraumatic stress disorder, hypertension, and heart failure, and also the structure of DBH described here, will facilitate further developments, because the inhibitor binding site and mode of action can be elucidated in detail." (PMID 27152332, 2016). "Therefore, it is inferred that in SAS patients, the upregulation of DBH and PNMT in neural cells in the adrenal medulla may induce hypertension, while miR-375 could play a crucial role in regulating the gene expression of DBH and PNMT." (PMID 36361741, 2022).
Anxiety (8 papers, 2012 to 2026). Intense feelings of nervousness, tension, or panic often arise in response to interpersonal stresses. "Disulfiram increases self-reported ratings of psychostimulant aversion, such as anxiety, nervousness, paranoia, craving, and dysphoria in humans, and addicts with polymorphisms in the DBH gene that confer low DBH activity report higher levels of cocaine-induced paranoia." (PMID 23209785, 2012). "In conclusion, DBH inhibitor nepicastat has an effect consistent with a decrease in the persistence of traumatic memories and anxiety-like behavior in this PTSD mice model." (PMID 34630037, 2021). "On day 7, in mice treated with nepicastat, there was an increase of Npas4 and Bdnf mRNA expression in the hippocampus.In conclusion, DBH inhibitor nepicastat has an effect consistent with a decrease in the persistence of traumatic memories and anxiety-like behavior in this PTSD mice model." (PMID 34630037, 2021). "Stress-induced anxiety was assessed in mice specifically lacking NA but expressing normal LC galanin levels (DBH KO) and in mice specifically lacking noradrenergic-derived galanin but showing normal LC-NA levels (GALcKO-Dbh)." (PMID 40749333, 2025).
migraine (7 papers, 2009 to 2015). "The functional DBH insertion/deletion polymorphism 19bp indel (-4784-4803) was found to associate with migraine in an Australian population." (PMID 24403849, 2013). "Also a promoter functional polymorphism (-1021C→ T, rs1611115) in DBH which reduces plasma enzyme activity by up to 52% was found associated with migraine aura in an Australian population." (PMID 24403849, 2013). "Multiple epidemiological studies have investigated the association between migraine susceptibility and polymorphisms of the four genes DRD2, COMT, DBH, and MAO-A." (PMID 26632697, 2015). "Some epidemiological studies have investigated the relationship between genetic polymorphisms of DRD2, COMT, DBH, and MAO-A and migraine susceptibility, but the results are still inconsistent." (PMID 26632697, 2015). "Risk variants and haplotypes in dopamine metabolism genes, DBH, DDC, MAOA, and SLC6A3, are reported to influence migraine risk, as are variants in the oestrogen receptor gene, ESR1." (PMID 22030984, 2011). "Other dopamine receptor and transporter gene SNPs were not linked to migraine in Spanish samples but dopamine transporter and dopamine beta-hydroxylase gene SNPs did show an association to migraine with aura in other European samples." (PMID 22110941, 2012). "Subsequent studies found association between migraine phenotypes and polymorphisms in DRD4 and DBH, although negative associations have also been described." (PMID 19772578, 2009). "Studied polymorphisms of DRD2, DBH, and MAO-A genes may not be associated with migraine susceptibility." (PMID 26632697, 2015).
Parkinson disease (7 papers, 2012 to 2025). A progressive degenerative disorder of the central nervous system characterized by loss of dopamine producing neurons in the substantia nigra and the presence of Lewy bodies in the substantia nigra and locus coeruleus. "A variant in a 3′ untranslated region, rs129882, has been associated with Parkinson’s disease in East India, and it also influenced the association in the C–A–T haplotype (rs1611115–rs1108580–rs129882) of the DBH gene." (PMID 36143905, 2022). "In our another studies, we have measured the various catecholamines and indoleamines mediating enzymes in Parkinson’s disease and other extrapyramidal diseases; it was observed that DBH activities were decreased significantly in all these diseases." (PMID 24711750, 2014). "The NA-synthesizing enzyme DA-β-hydroxylase (DBH) is crucial for NA synthesis and has been exploited for laboratory models: DBH knock-out mice do not produce NA and exhibit both parkinsonism and spontaneous dyskinesias, even if striatal DA is preserved." (PMID 37445461, 2023). "Despite its ability to express DBH in addition to TH, SH-SY5Y has widely been used to model dopaminergic neurons (which do not express DBH) to research Parkinson’s disease." (PMID 40071727, 2025).
cocaine dependence (5 papers, 2008 to 2025). A psychologically and socially impaired state, with or without physiological changes, that develops as a result of using cocaine and which leads to compulsive behaviors to acquire the substance. "This is the first study examining the effect of polymorphisms in the DbH gene and the susceptibility to cocaine addiction utilizing a case-control approach." (PMID 18173840, 2008). "Inhibitors of DBH (nepicastat and etamicastat) are currently in clinical development for treatment of cocaine dependence." (PMID 27152332, 2016). "Disulfiram has been claimed to be useful in cocaine addiction therapy, its efficacy being attributed to dopamine‐beta‐hydroxylase (DBH) inhibition." (PMID 26516613, 2015). "Pharmacological treatment studies with the DbH inhibitor disulfiram also indicate that this medication has efficacy as a treatment for cocaine dependence." (PMID 18173840, 2008). "The effect of disulfiram on maintaining abstinence or preventing relapse is mediated by DBH and/or ALDH inhibition as has been proposed in studies mentioned previously on cocaine dependence and pathological gambling." (PMID 24520330, 2014). "However, our study does not exclude a minor role for the DbH protein or its related pathway in the development of cocaine addiction and suggests that the examination of other variants within this gene not in close LD with the -1021C>T is necessary to completely rule out an effect." (PMID 18173840, 2008). "In summary, our results do not support a specific role for the -1021C>T in cocaine addiction in the Brazilian population or a major role for variation in enzymatic activity of DbH." (PMID 18173840, 2008).
autism (4 papers, 2009 to 2024). Persistent deficits in social interaction and communication and interaction as well as a markedly restricted repertoire of activity and interest as well as repetitive patterns of behavior. "Clostridia produces inhibitors of DBH, leading to excess dopamine and reduced norepinephrine, which are common in autism." (PMID 39328626, 2024). "Norepinephrine itself has a demonstrable role in encoding “unexpected uncertainty” in perceptual learning tasks, and norepinephrine/DBH abnormalities in autism are some of the earliest and most consistent neurobiological findings in people, and first-degree relatives, with autism." (PMID 24860482, 2014). "It focuses on the enzyme dopamine-beta-hydroxylase (DBH), which converts dopamine to norepinephrine, and how its activity is altered, contributing to autism symptoms." (PMID 39328626, 2024).
alcohol (3 papers, 2011 to 2022). "AP-2β activation of dopamine-beta-hydroxylase (DBH) may also contribute to alcoholism, since in alcohol-dependent persons, DBH is hypomethylated and its enzyme is more active, resulting in a reduction of dopamine levels." (PMID 36076256, 2022). "Disulfiram, an aldehyde dehydrogenase inhibitor as well as a dopamine-beta-hydroxylase (DBH) inhibitor, is approved for treatment of alcohol dependence." (PMID 22047090, 2011). "Furthermore, current clinical trials do not suggest the use of DBH inhibitors in the therapy of OUD or alcohol dependent subjects exhibiting comorbid opioid-related problems." (PMID 34236605, 2021).
noradrenaline deficiency (3 papers, 2016 to 2023). "For example, orthostatic hypotension-1 (OMIM #223360) is an autosomal recessive disorder characterized by mutations in dopamine beta hydroxylase (DBH), which converts dopamine to norepinephrine." (PMID 36357675, 2022). "In patients suffering from norepinephrine deficiency, four potentially pathogenic mutations in the DBH gene have been identified." (PMID 27152332, 2016). "This absence of NE role during brain early development is also in agreement with the observation in humans with noradrenaline deficiency or mice with a constitutive deletion of DBH, of a cardiac, but not central, phenotype." (PMID 36979445, 2023).
Obesity (3 papers, 2009 to 2018). Accumulation of substantial excess body fat. "Moreover, we observed candidate association of rs6271 in the DBH gene, rs62618693 in the QSER1 gene, and variants in PCDHA1, RAD51B, and PLEKHA5 with non-T2D-linked obesity." (PMID 30126146, 2018). "We also identified rs6271 in the DBH gene, and rs62618693 in the QSER1 gene as specific markers for obesity." (PMID 30126146, 2018).
Alzheimer disease (2 papers, 2022 to 2025). A progressive, neurodegenerative disease characterized by loss of function and death of nerve cells in several areas of the brain leading to loss of cognitive function such as memory and language. "In addition, there is a reduction in genotype‐independent plasma DBH activity in Alzheimer's disease, particularly in the early stage, compared to levels observed in the late stages of the disease and healthy individuals." (PMID 39517120, 2025).